INS (insulin)
Diseases named in the same sentence as INS in open-access papers (continued):
Sharing a sentence is not in itself a finding about the gene and the disease.
diabetes (continued). "Indeed, HS plasma, but not trauma or control plasma, is characterized by higher levels of glucose, which is consistent with an insulin-resistant or traumatic diabetes-like metabotype." (PMID 26242576, 2015). "Insulin is commonly prescribed to treat uncontrolled diabetes." (PMID 26187303, 2015). "In addition, the processes and pathways linking diabetes to cognitive impairment and dementia are varied and involve the role of insulin and chronic hyperglycaemia." (PMID 26193295, 2015). "The animal model of high-fat diet combined with STZ-induced diabetes manifests many characteristics of human diabetes, such as hyperglycemia, hyperlipemia, lack of insulin secretion, and loss of body weight." (PMID 26346939, 2015). "Pre-diabetes is an insulin resistant state that typically precedes diabetes and may lead to T2D when accompanied by a primary defect in the pancreatic β-cells." (PMID 25830378, 2015). "Aging is accompanied by an increase in glucose intolerance and the prevalence of type 2 diabetes mellitus, both of which result from an imbalance between the body's requirement for insulin (insulin sensitivity) and its ability to secrete insulin (β-cell function)." (PMID 26623014, 2015). "Reduction of Reg1 was linked with the pathogenesis of impaired glucose tolerance of diabetes, while treatment with Reg1 protein improved the islet β-cells ability to secrete insulin in rat models of diabetes, indicating its role in the pathogenesis of type 2 diabetes." (PMID 26568772, 2015). "Characteristics of 123 Japanese patients with insulin-treated diabetes." (PMID 26102197, 2015). "In the present study, we showed that in spite of a glucagon deficiency, HFD-fed Gcggfp/gfp mice did develop diabetes, which was due to impaired insulin secretion and not insulin resistance." (PMID 26378455, 2015). "This may indicate that insulin resistance, in addition to insulin secretion, plays a significant role in mediating the effects of proinsulin on the conversion to diabetes." (PMID 25853252, 2015). "Diabetes was defined using HbA1c (HbA1c ≥6·5% or history of diabetes diagnosis or using insulin or oral hypoglycaemic drugs) compared with either FPG only or FPG-or-2hOGTT definitions (FPG ≥7·0 mmol/L or 2hOGTT ≥11·1 mmol/L or history of diabetes or using insulin or oral hypoglycaemic drugs)." (PMID 26109024, 2015). "Persimmon leaves may also have a therapeutic potential against diabetes due to modulation of insulin dependent glucose transport." (PMID 27047315, 2015). "Plants used in the treatment of diabetes often exert their effects through increasing insulin secretion, increasing glucose reabsorption by skeletal muscle and adipose tissues, inhibiting intestinal absorption of glucose, and inhibiting hepatic glucose production." (PMID 25949955, 2015). "For diabetes treatment, metformin was added to insulin, with good glycaemic control (HbA1c < 7%)." (PMID 25885670, 2015). "Glucagonocentrism was proposed as a new framework to facilitate such results whereby a lack of insulin was proposed to lead to glucagon excess, in turn causing diabetes abnormalities." (PMID 26378455, 2015). "BALB/c mice had a relatively large islet mass, which may contribute to the high level of insulin secretion, the strong tolerance to glucose and the high resistance to diabetes compared to other strains." (PMID 25946019, 2015). "In-vitro expansion of insulin-producing cells from adult human pancreatic islets could provide an abundant cell source for diabetes therapy." (PMID 26418361, 2015). "The significance of LDH increase in diabetes is unknown; however this could be related to lower amount of insulin as insulin has been reported to affect the activity of LDH." (PMID 25852767, 2015). "Apart from the broad categories of the use of medical informatics in the health care area, its main applications with regard to diabetes have been grouped into three major categories: the prompting of diabetes care, insulin dose adjustment and patient education." (PMID 25902317, 2015).
diabetes (continued). "Furthermore, we excluded patients with type 1 diabetes mellitus to demonstrate a link with type 2 diabetes mellitus; and excluded the potential contamination of the use of insulin glargine or other insulin analogs to demonstrate a link with human insulin." (PMID 26537234, 2015). "Insulin treatment may prevent disorders of the growth hormone axis and allow normal growth in children with diabetes." (PMID 26457227, 2015). "Furthermore, DNA methylation, which irreversibly deactivates gene transcription, of the insulin promoter, particularly the cAMP response element, is increased in diabetes patients." (PMID 25658116, 2015). "The use of insulin for the treatment of diabetes can have a significant impact on patients’ quality of life, as well as generate additional costs to the health care system by providing additional supplies and equipment needed for safe and effective insulin therapy management." (PMID 26120575, 2015). "Taken together, our findings revealed the effects of the strongly interacting pair of Cdr1as/miR-7 on insulin secretion, which may become a new target for improving β cell function in diabetes." (PMID 26211738, 2015). "Because BDF1 mice are prone to develop obesity-induced diabetes more than B6 mice, our mutant mice could display better glucose tolerance and greater responsiveness to insulin." (PMID 26466345, 2015). "A search of PubMed for co-occurrence of the term “insulin” or “diabetes” with each of the 2,637 genes showed that less than half of these genes were mentioned in insulin or diabetes literature; thus, these results identified a large number of insulin-responsive genes." (PMID 26202599, 2015). "This study examines whether a high-protein diabetes-specific formula reduces insulin needs, improves glycemic control and reduces ICU-acquired infection in critically ill, hyperglycemic patients on mechanical ventilation (MV)." (PMID 26549276, 2015). "On average per month a patient in Bamako spent $21.24 on diabetes care (assuming 1 blood glucose measurement per month, 8 syringes per month, 1 vial of insulin at an average cost of $10.88 in the public sector, 1 monthly consultation, and travel costs) representing nearly 70% of per capita GDP." (PMID 25937831, 2015). "Compared to insulin, glucagon has long been dismissed as a minor contributor to diabetes." (PMID 26378455, 2015). "The relative or absolute insulin deficiency of diabetes may have rendered her less sensitive to the insulin-enhanced hepatic production of IGF-1 and may explain why her IGF-1 levels increased with insulin and metformin treatment." (PMID 26514337, 2015). "Thus, this ultra-long insulin analog is a relevant addition to the therapeutic armamentarium for diabetes." (PMID 26136850, 2015). "The effects remained significant after controlling for age, education, diabetes duration and insulin treatment, suggesting that the findings may be generalised to most type 2 diabetes patients suffering from subsyndromal depression." (PMID 26174334, 2015). "Significant elevation in HbA1c levels persisted after controlling for the confounding factors, namely, age, duration of diabetes mellitus, total energy intake, current drinking habits, regular exercise habits, depressive symptoms, use of oral hypoglycemic agents, use of insulin, and BMI." (PMID 25822499, 2015). "Reduced survival in insulin treated patients would not be unexpected due to insulin use being associated with obesity and poor diabetes control, both of which would predict increased noncancer deaths." (PMID 26074965, 2015). "Research into the effect of PCNT on insulin release may give a new way to prevent and control diabetes in a clinical setting." (PMID 26083368, 2015). "Possible insulin-sensitising and anti-inflammatory effect of omentin-1 could have a positive role in changes of cholesterol metabolism in diabetes mellitus type 1." (PMID 26524638, 2015).
diabetes (continued). "It is interesting to observe that loci common/shared between monogenic diabetes and T2D affect physiological processes like pancreatic beta cell development and function, glucose sensing mechanisms and their coupling with insulin release/secretion and endoplasmic reticulum (ER) stress." (PMID 26300908, 2015). "Normally, insulin therapy is initiated in a more advanced stage of diabetes." (PMID 26446829, 2015). "This has been reviewed previously in detail for drivers with insulin-treated diabetes." (PMID 28702227, 2015). "Failure to generate mitochondrial metabolic signals through NADH shuttles might contribute to impairment of glucose-induced insulin secretion seen in diabetes mellitus." (PMID 25970163, 2015). "Diabetes mellitus is characterized by disorders of insulin action or insulin secretion, either of which may be a predominant feature." (PMID 26464869, 2015). "In the 1990 ́s a National Diabetes Plan worked especially to guarantee greater access to insulin." (PMID 26617678, 2015). "To investigate whether glucose absorption is also decreased after IIP, we induced diabetes with decreased glucose tolerance and insulin sensitivity in male rats and investigated effects of IIP on diabetes and SGLT1." (PMID 26185767, 2015). "Clinical trials with rHuPH20 have been undertaken in the areas of rapid large volume hydration, rapid insulin and insulin analog delivery in subjects with diabetes, and delivery of large proteins such as immunoglobulins and monoclonal antibodies by SC rather than intravenous (IV) injections." (PMID 25967925, 2015). "However, the gradual decrease of cell function and activity after transplantation hindered the use of transplantation of insulin-secreting cell in the treatment of type 1 diabetes mellitus." (PMID 26688810, 2015). "Considering the epidemic of diabetes mellitus in the Asian population, being characterized by impaired insulin secretion and high smoking rate, these strengths may broaden the generalizability of the results." (PMID 25822499, 2015). "Our findings indicate that disease-specific iPSCs may help to better understand the mechanisms responsible for defective insulin production or vascular dysfunction upon differentiation toward cell types affected by diabetes." (PMID 25716801, 2015). "Insulin is one of the most studied proteins since it is central to the regulation of carbohydrate and fat metabolism in vertebrates and its expression and release are disturbed in diabetes, the most frequent human metabolic disease worldwide." (PMID 25774519, 2015). "Treatment with continuous s.c. insulin infusion (CSII) provides better glycemic control for patients with type 1 diabetes mellitus than conventional therapy with multiple daily insulin injections, with a lower frequency of hypoglycemia and lesser insulin doses." (PMID 25614824, 2015). "First, in the present study, we used db/db mice that are insulin-resistant and diabetics." (PMID 26230680, 2015). "Therefore, it is important for patients with insulin-treated diabetes to prevent mild as well as severe hypoglycemia, and to identify predictors for mild and severe hypoglycemia." (PMID 26102197, 2015). "On the other hand, it has been reported that insulin clearance is increased in subjects carrying diabetes-susceptible gene, and that insulin clearance is not affected by decreasing insulin secretion by free fatty acid administration." (PMID 26623647, 2015). "Using this novel informatics approach, it is clear that multiple metabolic aspects (“mitochondria,” “diabetes,” “insulin,” “glucose,” “electron transfer chain,” “fat,” “energy,” “aging”) demonstrate, at these early life timepoints, a coherent age-dependent increase." (PMID 26834700, 2015). "Based on the insulin levels and pancreatic function, two main types of diabetes are recognized." (PMID 25866533, 2015).
diabetes (continued). "We also investigated changes in plasma chemerin levels and chemerin gene mRNA content in adipose tissue in models of obesity and diabetes, and in response to fasting or administration of the insulin sensitizing drug rosiglitazone, which also has anti-inflammatory properties." (PMID 25699203, 2015). "In our study HFD/STZ rats exhibited weight loss and hyperglycaemia, which could be considered indicative of type 1 diabetes mellitus; however, there was measurable and functional insulin present throughout the study duration, mimicking type 2 diabetes." (PMID 25759824, 2015). "Over time, with the structuring of distribution systems and purchasing processes, and a clearer allocation of responsibilities among different administrative levels of the system, the magnitude of the problem of availability of insulin, other diabetes medications, and supplies diminished greatly." (PMID 26259708, 2015). "Although some authors assume that being on insulin treatment might be related to the duration of the disease, in our study the effect of insulin was present even after controlling for the duration of diabetes." (PMID 25925666, 2015). "In the study of the Diabetes in Pregnancy Center at Northwestern University in Chicago, diabetes during pregnancy, including both GDM and insulin-treated preexistent diabetes, was associated with increased BMI of the offspring at birth and after the age of 5 years." (PMID 25802854, 2015). "Furthermore, inhibition of NFκB using SN50 reversed gene profile related to development of insulin resistance and diabetes and improved skeletal muscle insulin signaling." (PMID 25928697, 2015). "Liraglutide may exhibit favorable effects on diabetes control for type 2 DM patients by increasing insulin sensitivity as an extrapancreatic action." (PMID 25922845, 2015). "A possible explanation for this result is that the patients on pre-prandial bolus insulin may have diabetes that is more difficult to control." (PMID 26120575, 2015). "Indeed, this unique property of boronic acid has recently been exploited for an enhanced delivery of insulin for treatment of diabetes." (PMID 26354796, 2015). "However, anticancer drugs, docetaxel and doxorubicin, and insulin in diabetes cannot be delivered orally because of their low oral bioavailability for various reasons." (PMID 26448753, 2015). "Even at the ITP dosage of 14 PPM, sustained periods of treatment may result in abnormal insulin and glucose responses reminiscent of diabetes." (PMID 26257774, 2015). "With respect to diabetes control, 51% of patients were receiving insulin by subcutaneous infusion." (PMID 26242308, 2015). "In our study, HbA1c, HOMA-IR, and plasma insulin per se were associated with an increased risk of liver cancer mortality among those without diabetes, a finding that is consistent with previous epidemiologic studies." (PMID 26250516, 2015). "Insulin gives me more control, and means I can do more than sit around worrying about diabetes." (PMID 26075285, 2015). "There appear to be differential effects of elevated levels of glucose and insulin during the prodromal/early stages of diabetes on the development of prostate cancer, compared with the influence of fully developed diabetes on the risk of prostate cancer mortality." (PMID 26250516, 2015). "High insulin/IGF is a biologic link between diabetes and cancer." (PMID 26268733, 2015). "Recently, FDA approved Accu-Check Aviva Expert glucose meter with built-in insulin advisor as it has shown to improve glycemic control and treatment satisfaction without increasing severe hypoglycemia in insulin requiring patients with diabetes." (PMID 28702234, 2015). "According to a previous systematic review, individuals of East Asian descent, which includes Japanese people, have higher insulin sensitivity than people from Western countries, whereas the insulin secretory ability is low only in East Asian individuals with diabetes." (PMID 26215867, 2015).
diabetes (continued). "The study was a great success and confirmed insulin's effectiveness in treating diabetes." (PMID 26180777, 2015). "This polymorph could provide the possibility of supplying a larger amount of insulin with smaller drug doses and thereby reducing the frequency of dosing in people with diabetes." (PMID 26306195, 2015). "Although further studies are necessary, it is important too to comment that high insulin doses required for tight diabetes control may result in higher weight gain during pregnancy and this might be adding insult to injury." (PMID 25885892, 2015). "Similar to European regulations, drivers with insulin-treated diabetes may be able to obtain a driving license for commercial vehicles such as large trucks, but may not be able to cross state boundaries." (PMID 28702227, 2015). "Diabetes mellitus is a metabolic disorder caused by a lack of insulin characterized by hyperglycemia." (PMID 25887244, 2015). "Type 1 diabetes mellitus is characterized by high blood glucose level caused by the lack of insulin-secreting cells (β cells)." (PMID 26688810, 2015). "These relationships remained significant even after adjusting for confounding factors, namely, age, duration of diabetes mellitus, total energy intake, current drinking habits, regular exercise habits, depressive symptoms, oral hypoglycemic agent use, insulin use, and BMI." (PMID 25822499, 2015). "Therefore, diabetes remission was more unpronounced in patients requiring insulin therapy compared with prescribed oral hypoglycemic agents." (PMID 25103403, 2015). "These could include the direct effects of hyperglycemia as well as secondary physiologic responses to hyperglycemia (e.g., insulin and the effects of the insulin-like growth factor system) and treatment of diabetes." (PMID 26250516, 2015). "Insulin dropped sharply after induction of diabetes (p<0.005)." (PMID 26445712, 2015). "Diabetes mellitus (DM) is characterized by a hyperglycemic postprandial state due to apartial or total absence of insulin released by pancreatic beta cells, peripheralresistance to insulin, or both." (PMID 26421869, 2015). "Derangement of insulin signaling pathways such as the impaired activation of the phosphatidylinositol 3-kinase and downstream signaling is thought to be responsible for the onset of insulin resistance and diabetes." (PMID 26475130, 2015). "However, loquat has been shown to produce tormentic acid that not only improves symptoms of diabetes but also increases insulin production." (PMID 26848337, 2015). "However, normal progression of the disease often leads to the need for insulin therapy for glycemic control and prevention of diabetes complications." (PMID 26120575, 2015). "It has been suggested that diabetes may be linked to the development and progression of pancreatic cancer as 80% of pancreatic cancer patients experience some form of diabetes or altered insulin sensitivity." (PMID 25919692, 2015). "Most patients with type 1 diabetes mellitus receive intensive insulin therapy." (PMID 26819737, 2015). "Another concern regarding diabetes and malignancy involves insulin therapy." (PMID 25978841, 2015). "A British study suggested that drivers with insulin-treated diabetes were not at increased risk, but one confounding factor was that the percentages holding a driving license in populations with and without diabetes were not determined." (PMID 28702227, 2015). "Thus, at treated cells with gingerol, insulin responsive glucose uptake has increased and improved diabetes." (PMID 25561919, 2015). "As many challenges exist for access to diabetes care in developing countries, the International Insulin Foundation developed a Rapid Assessment tool and implemented this approach to identify barriers to care and propose concrete recommendations for decision makers." (PMID 26427953, 2015). "Replenishment of insulin-producing pancreatic β-cells would be beneficial in diabetes." (PMID 26510947, 2015).